EGR1 (early growth response 1)
Diseases named in the same sentence as EGR1 in open-access papers (continued):
Sharing a sentence is not in itself a finding about the gene and the disease.
prostate carcinoma (continued). "Overexpression of EGR1, GDF15 and MYC in prostate cancer was previously reported in the literature." (PMID 28005952, 2016). "For example, STAT3, AP1, AR, ERG, EGR1 and MYC are important TFs that are responsible for the progression of prostate cancer by affecting a wide variety of pathways involved in cell proliferation and differentiation, apoptosis, tumor suppressing and various cell signaling pathway." (PMID 28005952, 2016). "Egr1 and Egr3 bind to similar sequence motifs on promoters and it is therefore unsurprising that they share a set of target genes such as IL6 and IL8, which we have now validated as direct targets for Egr3 in prostate cancer cells." (PMID 23342084, 2013). "Another study reported that EGR-1 upregulation and nuclear translocalization could be regulated by 2′-Benzoyloxycinnamaldehyde (BCA), activating proapoptotic target genes and inducing prostate cancer cell death." (PMID 36233659, 2022). "Based on our knowledge of Egr1 and the common DNA binding characteristics of all EGR transcription factors, we hypothesize that Egr3 does indeed play a role in either the formation or progression of prostate cancer." (PMID 23342084, 2013). "Moreover, tumour progression in transgenic mouse models of prostate cancer was reported to be significantly impaired when Egr-1 was not expressed." (PMID 20087343, 2010).
gastric cancer (53 papers, 2010 to 2025). A primary or metastatic malignant neoplasm involving the stomach. "As a transcription factor, EGR1 has been implicated in the carcinogenesis of breast cancer and gastric cancer and so forth through regulating the transcription activity of specific target genes." (PMID 34409922, 2021). "In some cancers EGR1 inhibits growth where as in others EGR1 is associated with tumor progression, for instance in prostate and gastric cancer which possess endocrine components." (PMID 25546138, 2014). "In fact EGR1 has been reported to play a role in prostate tumor growth and survival and its abnormal expression has been recently associated with tumor invasion and metastasis in gastric cancer." (PMID 24148231, 2013). "It has been shown that both LINC01503 and early growth response protein 1 (Egr-1) are significantly higher in the serum of patients with gastric cancer and the correlation with LINC01503 levels in gastric cancer tissue." (PMID 40191723, 2025). "Abnormal expression of EGR1 has been identified in prostate and gastric cancers, thus functioning as an oncogene." (PMID 40361912, 2025). "Its expression varies across tumor types, acting as an oncogene in prostate and gastric cancers, where higher EGR1 levels correlate with increased malignancy and poor prognosis." (PMID 41155227, 2025). "In gastric cancer, EGR1 promoted the transcription of linc01503 and further affected the cell cycle." (PMID 36932397, 2023). "Surprisingly, contrary results have been reported for the role of EGR1 in gastric cancer 20,21, the mechanism of which is still unclear." (PMID 35069903, 2022). "EGR1 has been reported to promote gastric cancer cell cycle progression and tumorigenesis through the mediated linc01503." (PMID 35223996, 2022). "EGCG suppresses recepteur d’origine nantais (RON) expression in gastric cancer cells by inhibiting Egr-1 (-) and blocked MMP-9 expression induced by nicotine in endothelial cells." (PMID 36430487, 2022). "Apart from acting as a tumour suppressor, EGR1 has also been shown to promote cancer development, including prostate, lung, and gastric cancers." (PMID 35563324, 2022). "Numerous studies have shown that the EGR1 gene is closely related to tumors, stomach cancer, glioma and melanoma; however, little is known about the direct effect of EGR1 on dermal papilla cells." (PMID 35886025, 2022). "In gastric cancer, EGR1 has been reported to enhance tumor cell proliferation and invasion by increasing β-catenin expression." (PMID 33842351, 2021). "EGR1 has been demonstrated to inhibit the transcription activity of anti-oncogenic miR-195 and reduce the apoptosis of gastric cancer cells." (PMID 34409922, 2021). "There has been a similar finding in gastric cancer: patients whose tumor is histologically classified as malignant exhibit higher tumor EGR1 levels and a stronger ability of tumor cells to proliferate." (PMID 33842351, 2021). "Of note, in gastric cancer, the upregulation of the transcription factor EGR1 results in enhanced transcription of lncRNA-HNF1A-AS1 and in the promotion of cell proliferation." (PMID 32076467, 2020). "The roles of proteasome subunit beta type-8 (PSMB8) and EGR1 in trastuzumab-resistant gastric cancer are controversial." (PMID 31949544, 2019). "We found that the expression of EGR1 was increased in gastric cancer (GC), and silencing the expression of EGR1 promoted the apoptosis of GC cells." (PMID 31515938, 2019). "Investigation is shown that EGR1 is involved in early stage as well as progression of gastric cancer." (PMID 30425814, 2018). "Literature mining informed us that FOXO1 and EGR1 have been implicated in HCC, and ZIC1 is down-regulated in gastric cancer and has been proved to be a tumor suppressor gene in colorectal cancer." (PMID 24278165, 2013).
gastric cancer (continued). "Egr-1 basal expression was also found to be much higher in gastric cancer tissues than in normal gastric mucosa and high Egr-1 mRNA expression correlated with metastasis to lymph nodes and remote organs." (PMID 20087343, 2010). "Bioinformatics analyses revealed decreased EGR1 expression alongside increased NEDD4L expression in gastric cancer, suggesting EGR1 may bind the NEDD4L promoter to regulate its transcription." (PMID 41561975, 2025). "Wu and colleagues reported that pyruvate kinase M2 (PKM2) within exosomes derived from gastric cancer cells can be internalized by TAMs, resulting in upregulation of early growth response factor 1 (Egr-1) within TAMs and leading to the M2 polarization of TAMs and the promotion of tumor progression." (PMID 39889181, 2025). "Besides, emerging and increasing evidence has shown Egr1 is closely related with tumor progression in gastric cancer." (PMID 37989866, 2024). "Likewise, the transcription factor EGR1 has been demonstrated to modulate the proliferation of astrocytes, smooth muscle cells and gastric cancer cells." (PMID 38256034, 2024). "Several pieces of evidence declared EGR1 as an oncogene-like molecule in gastric cancer." (PMID 37188478, 2023). "EGR1 has been reported to promote cell proliferation in prostate, lung, and gastric cancers." (PMID 35563324, 2022). "Furthermore, previous study has demonstrated that EGR1 transcriptionally activated HNF1A-AS1 in human gastric cancer." (PMID 34772911, 2021). "REC8 have been proved to inhibit gastric cancer cell EMT by down-regulating EGR1 expression." (PMID 34889158, 2021). "The expression of EGR1 was lower in primary gastric cancer samples than in normal samples." (PMID 31949544, 2019). "Therefore, the roles of PSMB8 and EGR1 in trastuzumab-resistant gastric cancer need to be further investigated." (PMID 31949544, 2019). "Besides, there are some reports implicating EGR1 in colorectal and gastric cancer cell proliferation and metastasis." (PMID 26498686, 2015). "Therefore, EGR1 plays an oncogenic part in prostate and gastric cancers." (PMID 33842351, 2021). "In addition, Zhao and colleagues proposed that the downregulation of EGR1 in gastric cancer cells might influence EMT." (PMID 33276775, 2020). "Yangbing Jin and colleagues reported that the interaction of EGR1/TGF-β1/CD44s/STAT3 signaling between mesenchymal cells and gastric cancer cells induces EMT and the stem phenotype, leading to the peritoneal metastasis of gastric cancer cells." (PMID 39309860, 2024). "Egr1 could prompt EMT of non-small cell lung cancer (NSCLC) and gastric cancer cells and activate gastric cancer cells proliferation and invasion by stimulating β-catenin expression." (PMID 37989866, 2024). "Subsequently, both EGR1 and HNF1A-AS1 inhibit p21 via activation of CDK2 and CDK4, adding another layer of regulatory mechanisms involved in the function of CDK2 in the development of gastric cancer." (PMID 36769170, 2023). "EGR1 may interact with DNMT3L, inhibit the miR-195-AKT3 axis, and regulate gastric cancer cell apoptosis." (PMID 36120336, 2022). "In gastric cancer, HNF1A-AS1 induced by EGR1 was shown to promote the cell cycle as well." (PMID 36230970, 2022). "Finally, the expression of four hub genes (ERBB2, VIM, EGR1, and PSMB8) was found to be related to the prognosis of HER2-positive (HER2+) gastric cancer." (PMID 31949544, 2019).
lung carcinoma (52 papers, 2005 to 2026). "Herein, we developed the first multiplexed mouse model to study the impact of TBX2 subfamily loss, alongside associated signaling genes (Egr1, Chd2, Tnfaip3a, and Atf3) in Ras-driven lung cancer." (PMID 41705258, 2025). "Our results suggested that EGR1 functions as an onco-suppressor, and the inhibition of EGR1 was associated with tumor aggressiveness in lung cancer." (PMID 34497759, 2021). "To understand how EGR1 affects the expression status of its downstream target genes in YYJD‐treated lung cancer cells, we analysed the EGR1‐associated transcription network by intersecting ChIP‐seq data with the transcriptome data." (PMID 31237749, 2019). "Blocking nuclear translocation of Egr-1 is responsible for the loss of PTEN expression in gefitinib-resistant lung cancer cells." (PMID 25004251, 2014). "Moreover, shikonin causes apoptosis in some lung cancer cell lines via the FOXO3a/EGR1/SIRT1 signaling pathway activation." (PMID 31956359, 2020). "EGR1 depletion has been associated with tumor anti-apoptotic and invasion events, whereas its overexpression may depress the tumorigenicity and metastasis in different cancer cells, including lung cancer." (PMID 34497759, 2021). "TCGA (The Cancer Genome Atlas) database and the other two datasets supported in Lung Cancer Explorer confirmed that EGR1 was downregulated in NSCLC patient tissues compared to normal tissues." (PMID 34497759, 2021). "FOXO3a can increase Bim expression and stimulate lung cancer cells’ apoptosis, which is partly mediated by early growth response protein 1 (EGR1), which binds to the Bim promoter region." (PMID 34769241, 2021). "High expression of EGR1 has been observed in various tumors, in which EGR1 can play an oncogenic role, e.g., glioma, lung cancer, gastrointestinal tumors, and melanoma." (PMID 33842351, 2021). "In contrast, in lung cancer cell lines the apoptosis induction by SHI has been attributed to the FOXO3a/EGR1/SIRT1 pathway." (PMID 33672520, 2021). "EGR1 is reported to directly initiate VEGFA expression in lung cancer cells by binding to the VEGFA promoter and to increase angiogenesis by enhancing HIF1α-mediated VEGFA expression." (PMID 33842351, 2021). "Some of these genes, e.g., EGR1 and UNC5B, are known to be associated with different cancers, including lung cancer." (PMID 33711952, 2021). "In a human lung cancer xenograft model, Oct4-overexpressing tumors expressed elevated levels of Egr1." (PMID 31399076, 2019). "Collectively, these findings suggest that YYJD exerts its anticancer activities through EGR1 activation, thus providing the evidence for its potential clinical application for lung cancer patients." (PMID 31237749, 2019). "In the present study, we aimed to determine the association and clinical relevance of Oct4, Egr1, and OPN in lung cancer and to identify the related pathways and potential therapeutic strategies for the treatment of lung cancer." (PMID 31399076, 2019). "We indicated here that Egr-1 regulated CTSL-mediated cisplatin resistance in lung cancer by affecting the activity of CTSL promoter." (PMID 31370861, 2019). "There is controversy in several previous reports regarding the growth inhibition of lung cancer cells by overexpression of Egr1." (PMID 31399076, 2019). "Our results have confirmed that in the axis of Oct4-overexpressing cancer cells, Egr1 is upregulated and has oncogenic effects on the invasiveness and metastasis of lung cancer cells both in vitro and in vivo." (PMID 31399076, 2019).
lung carcinoma (continued). "Therapeutic strategies targeting the Oct4/Egr1/OPN axis pose a potential option for improving the grave course of lung cancer and the high resistance to systemic lung cancer treatments." (PMID 31399076, 2019). "Collectively, these results demonstrate that Oct4 can enhance the migration of lung cancer cells through Egr1." (PMID 31399076, 2019). "Here, we demonstrate that Oct4 is involved in OPN expression through upregulating Egr1 expression in lung cancer metastasis." (PMID 31399076, 2019). "Roles of cancer stem cells and early growth response gene 1 (Egr1) in carcinogenesis have been extensively studied in lung cancer." (PMID 31399076, 2019). "Such YYJD‐induced EGR1 activation was also observed in lung cancer cell lines NCI‐H2228 and NCI‐H1299." (PMID 31237749, 2019). "The wild-type epidermal growth factor receptor or MET receptors can sustain the survival of lung cancer cells via Egr1 and/or the extracellular signal-regulated protein kinase (ERK) 1/2." (PMID 31399076, 2019). "Shikonin induced apoptosis of lung cancer cells via activation of Forkhead box O3 (FOXO3a)/early growth response protein 1 (EGR1)/Sirtuin 1 (SIRT1) signaling antagonized by p300." (PMID 30420490, 2018). "More relevant to lung cancer, EGR1 expression can predict the expression of its putative downstream target PTEN37; this is also in agreement with our data." (PMID 28928421, 2017). "Our finding that CISD2 silencing-induced ROS can promote the expression of putative tumor suppressor EGR1 is also novel to lung cancer biology." (PMID 28928421, 2017). "Collectively, these findings provide novel mechanisms through which IGF-I/IGF-IR transduction signaling regulates GPER target genes like CTGF and EGR1 in mesothelioma and lung cancer cells." (PMID 27384677, 2016). "Other genes such as EGR1 are also differentially regulated in lung cancer and melanoma cells by those inhibitors." (PMID 22701735, 2012). "In breast, colon and lung cancer, fibrosarcoma and glioblastoma, Egr1 is considered a tumor suppressor gene, but Egr1 can act both as a tumor suppressor and as a tumor promoter, depending on the cell context." (PMID 22912725, 2012). "EGR1 plays an important role as a tumor suppressor in breast, brain and lung cancer, as EGR1 is poorly expressed in these tissues and acts as a suppressor of growth and transformation when overexpressed." (PMID 23029358, 2012). "Perhaps there are tissue-specific factors (either transcription factors or transcription factor co-activators/co-repressors) that respond differently to 5-aza-dC and TSA, leading to differential induction of MIG-6 and EGR1 in lung cancer and melanoma cells." (PMID 22701735, 2012). "Recently, isochaihulactone was shown to upregulate NAG-1 expression in the human lung carcinoma cell line A549 through an ERK-dependent pathway involving the activation of EGR-1." (PMID 21504622, 2011). "Moreover, we also observed that ANKRD1 and ATF3, as the target genes of EGR1, were significantly downregulated in malignant transformed cells and mice lung cancer tissues." (PMID 34497759, 2021). "Besides, β−catenin, the key effector of canonical Wnt signaling, was activated in malignant transformed cells and lung cancer tissues following EGR1 inhibition." (PMID 34497759, 2021). "EGR1 has a promoting effect on cancer metastasis in OCT4-overexpressing lung cancer." (PMID 33711952, 2021). "To further determine whether EGR1 downregulation was involved in human lung carcinoma development, we expanded our study by investigating the expression of EGR1 in clinical cancer tissues." (PMID 34497759, 2021).